CDH6 (cadherin 6)
Diseases named in the same sentence as CDH6 in open-access papers (continued):
Sharing a sentence is not in itself a finding about the gene and the disease.
melanoma (2 papers, 2013 to 2020). A malignant, usually aggressive tumor composed of atypical, neoplastic melanocytes. "Mutational co-occurrence and physical dynamics analyses placed CDH6 at the center of the top-four mutated cadherins (core CDHs; all type-II), suggesting altered heterophilic interactions in melanoma development." (PMID 33204327, 2020). "By using the immunogenetic dataset from MSKCC group 39, we also noticed patients with mutations in CDH6 or other core CDH genes showed more γδT cell recruitments in melanoma lesions with more activated CD4+ memory T cells and higher cytolytic scores." (PMID 33204327, 2020). "Nevertheless, the S524L substitution on the fifth extracellular (EC5) domain of CDH6 (K-cadherin) stood out to be a unique mutation with a relatively higher frequency, indicating its potent role in melanoma development." (PMID 33204327, 2020). "Thus, mutations in type-II cadherins, especially in CDH6, may gain functional advantages during melanoma development." (PMID 33204327, 2020). "Interestingly, we also found nuclear staining for mutated CDH6 in tumor samples, which could be novel phenomena in certain types of melanoma awaiting further investigation." (PMID 33204327, 2020). "Especially, the S524L substitution in CDH6 has been predicted to be a strong neo-antigen, peptides with such substitution could be utilized as potent adjuvants to trigger stronger anti-melanoma immunity when co-treated with other immuno-therapeutics such as anti-PD-1/L1 or anti-CTLA4 Abs." (PMID 33204327, 2020).
nasopharyngeal carcinoma (2 papers, 2021). A carcinoma arising from the nasopharyngeal epithelium. "On the other hand, there is evidence of an increase in cadherin-6 in LMP1-positive tissues of nasopharyngeal carcinoma, which can induce EMT and promote metastasis of nasopharyngeal carcinoma." (PMID 34603767, 2021).
serous ovarian cancer (2 papers, 2021).
Arthritis (1 paper, 2025). Inflammation of a joint. "Our studies focused on in vitro assays, and the effect of CDH6-directed approaches in pre-clinical arthritis models would be helpful." (PMID 40877928, 2025).
autism (1 paper, 2015). Persistent deficits in social interaction and communication and interaction as well as a markedly restricted repertoire of activity and interest as well as repetitive patterns of behavior. "Subject HI0855 possessed a variant of CDH6 located on chromosome 5 encoding a known cadherin playing a role in cell-cell adhesion and implicated in autism." (PMID 25574603, 2015).
cardiac hypertrophy (1 paper, 2016). "Specifically, markers of non-cardiac differentiation, such as those for vascular endothelium (VWF) and non-cardiac muscle (CDH6, CNN2 and MYLK) were downregulated, while genes encoding for cardiac hypertrophy (IGF1R) and calcium handling (CAMK2B) were upregulated." (PMID 26785135, 2016).
cervical cancer (1 paper, 2022). A primary or metastatic malignant neoplasm involving the cervix. "We previously found that CDH6, YAP1, and OCT4 transcripts were highly expressed in the HeLa (cervical) cancer cell line." (PMID 35356283, 2022). "Moreover, YAP1, CDH6 and OCT4 were significantly up-regulated in cervical cancer (p = 0.038, 8.98E-7 and 0.002, respectively)." (PMID 35356283, 2022).
chronic kidney disease (1 paper, 2020). Impairment of the renal function secondary to chronic kidney damage persisting for three or more months. "In a transcriptional analysis of human kidney organoids derived from pluripotent stem cells, CDH6 mRNA was identified as highly expressed in immature glomerular epithelial cells and reactivated in injured podocytes in chronic kidney diseases, including DKD." (PMID 32425885, 2020).
cutaneous melanoma (1 paper, 2020). A primary melanoma arising from atypical melanocytes in the skin. "Among AJ genes in cutaneous melanoma, CDH6 stood out to be a very interesting one which showed the highest mutation rate with several novel functional mutations." (PMID 33204327, 2020).
deafness (1 paper, 2023). An inherited or acquired condition characterized by the complete loss of the ability to hear from one or both ears. "Defects in the 30 shared genes are related to several pathologies, such as vision abnormalities (TMEM135), cancer (CDH6, FZD10, TIAM2), neuropsychiatric disorders (Tenm4, Pde4dip, Grid2), deafness (TFB1M), neutrophil disorders (VPS45) and others." (PMID 36902345, 2023).
dementia (1 paper, 2022). Loss of intellectual abilities interfering with an individual's social and occupational functions. "For example, CSF levels of the CDH6 protein were recently shown to be significantly associated with CSF p-tau and t-tau levels as well as amyloid-beta in a large cohort of dementia patients." (PMID 35982059, 2022).
diabetic nephropathy (1 paper, 2021). "According to previous studies, B3GALT2 was previously shown to be downregulated in a mouse model of diabetic nephropathy, and CDH6 was upregulated in renal fibrosis mice." (PMID 34332599, 2021).
endometrioid tumor (1 paper, 2025). A benign, borderline, or malignant epithelial tumor of the female reproductive system characterized by the presence of glands and/or cysts lined by neoplastic cells that resemble endometrial cells. "Additionally, we found that 3+ expression of HER2, FRα, and CDH6 was more frequently observed in non-endometrioid tumors than in endometrioid tumors, consistent with the findings from PDX models." (PMID 40199194, 2025).
hepatocellular carcinoma (1 paper, 2022). A malignant tumor that arises from hepatocytes. "Since it is well known that liver fibrosis is a dangerous risk factor for tumorigenesis, the high expression of CDH-6 may play an important role in the development of hepatocellular carcinoma from liver fibrosis." (PMID 36017335, 2022).
Hypertension (1 paper, 2023). The presence of chronic increased pressure in the systemic arterial system. "The likely pathogenic variations in CDH6, SRFBP1 and LAMA2 may assist in disorganization of the ECM components and cytoskeleton, leading to hypertension." (PMID 36833422, 2023).
Immunodeficiency (1 paper, 2006). Failure of the immune system to protect the body adequately from infection, due to the absence or insufficiency of some component process or substance. "Our data also supports the fact that immunodeficiency is correlated with altered calcium ion binding (UTRN, ID: AA676840; CDH6, ID: AA421819, CASQ2, ID: AA055163) and also is influenced by calcium- activated chloride channels (CLCA2, ID: AI675394) of host cells." (PMID 16956415, 2006).
ischemia (1 paper, 2021). A hypoperfusion of the BLOOD through an organ or tissue caused by a PATHOLOGIC CONSTRICTION or obstruction of its BLOOD VESSELS, or an absence of BLOOD CIRCULATION. "Under nonischemic conditions, pericytes expressed Cdh19, Cdh6, Cdh10, Cdh4, Cdh13, and Cdh5; after ischemia, the cadherin genes that were predominantly expressed were Cdh15, Cdh11, Cdh3, and Cdh2." (PMID 33726849, 2021).
kidney cancer (1 paper, 2021). Primary or metastatic malignant neoplasm involving the kidney. "Despite the high expression of α2β1 integrin in the plasma membrane of ovarian and kidney cancer cells, our results indicate a preferential binding of CDH6 to αIIbβ3 integrin whenever it is present." (PMID 33715292, 2021).
liver cancer (1 paper, 2022). An epithelial or non-epithelial malignant neoplasm that arises from the liver. "At the same time, CDH6 and OCT4 were both up-regulated significantly in liver cancer compared to normal controls." (PMID 35356283, 2022).
liver disease (1 paper, 2012). "Genes of inflammation and immunity (CD276, CDH6, GCKR, HNF1A, HPR, ITGA1, RORA, and STAT4) have been shown to be expressed in liver disease patients." (PMID 22530132, 2012).
liver fibrosis (1 paper, 2022). "The interaction between GRS and CDH-6 in damaged tissues and cells may enable the development of a novel druggable mechanism for treating liver fibrosis." (PMID 36017335, 2022).
multiple myeloma (1 paper, 2025). "For example, a high level of tri-methylation on lysine 27 of histone H3 (H3K27me3) at the CDH6 gene locus is observed in multiple myeloma cells, and this modification correlates with low CDH6 expression." (PMID 40877928, 2025).
myopia (1 paper, 2010). "Six candidate genes CDH6, CDH10, CDH12, PDZD2, GOLPH3, and ZFR at this high myopia locus were selected on the basis of their function to screen for gene mutations by re-sequencing." (PMID 21042559, 2010).
Nephroblastoma (1 paper, 2025). An embryonal neoplasm characterized by the presence of epithelial, mesenchymal, and blastema components. "In the CDH6-low kidney nephroblastoma PDX model, CUSP06 exhibited complete tumor growth inhibition (130% TGI vs. IgG-T1000-e control) whereas the R-DXd showed little antitumor activity (23% TGI vs. IgG-DXd control)." (PMID 40871070, 2025). "In a CDH6-low kidney nephroblastoma PDX model (LD-2511, CDH6 H-score = 80) a single dose of 10 mg/kg CUSP06 significantly repressed the tumor growth compared to the IgG-T1000-e control." (PMID 40871070, 2025).
osteoarthritis (1 paper, 2025). A noninflammatory degenerative joint disease occurring chiefly in older persons, characterized by degeneration of the articular cartilage, hypertrophy of bone at the margins and changes in the synovial membrane. "In transcriptome expression studies, we observed that Cadherin 6 (CDH6) expression was higher in RA compared to osteoarthritis (OA)." (PMID 40877928, 2025).
prostate carcinoma (1 paper, 2021). A carcinoma that arises from epithelial cells of the prostate gland. "It was therefore suggested that CDH6 may be involved in the regulation of PSMA-related prostate cancer metastasis mechanisms." (PMID 34880371, 2021).
pterygium (1 paper, 2021). A wedge-shaped fibrovascular lesion arising from the bulbar conjunctiva and extending to the cornea. "Moreover, CDH5 and CDH6, two important epithelial cell adhesion factors, were highly expressed in pterygium tissues investigated in this study." (PMID 33790949, 2021).
thrombosis (1 paper, 2025). "For example, CDH6 interacts with αIIb/ß3 on platelets and is associated with thrombosis in humans but operates through a different non-platelet mechanism in mice." (PMID 40877928, 2025).
triple-negative breast carcinoma (1 paper, 2022). An invasive breast carcinoma which is negative for expression of estrogen receptor (ER), progesterone receptor (PR), and human epidermal growth factor receptor 2 (HER2). "Additionally, CDH6 correlated with stem-cell-related transcription factors, including FOXM1, SNAI1, SOX9, and MCM2, in triple-negative breast cancer." (PMID 35938030, 2022).
uterine cancer (1 paper, 2025). Primary or metastatic malignant neoplasm involving the uterine corpus and/or the cervix. "CUSP06 also demonstrated dose-dependent tumor growth inhibition in a CDH6-medium uterine cancer PDX model (UT-3705, CDH6 H-score = 195)." (PMID 40871070, 2025).
cancer (48 papers, 2011 to 2025). A tumor composed of atypical neoplastic, often pleomorphic cells that invade other tissues. "CDH6 has been implicated in tumor progression and cancer metastasis, potentially through its effects on migration, autophagy, and cell growth." (PMID 40877928, 2025). "CDH6 is associated with cancer progression, but little information is known on the role of CDH6 in RA." (PMID 40877928, 2025). "Of note, several cancer associated genes such as CDH6, FOXM1, NAAA and CXCL10 were amplified and upregulated." (PMID 36352274, 2022). "Both tumor-suppressing 46, 47 and pro-oncogenic activities 45, 48, 49 were associated with CDH6 expression in cancer development." (PMID 33204327, 2020). "CDH6 function has been implicated in cancer cell migration, invasion, and cell growth." (PMID 40877928, 2025). "Similarly, the oncogene CDH6 is a well-known oncogene and has been linked with poor outcome in other cancer entities." (PMID 36352274, 2022). "In summary, GLP tox study results indicate CUSP06 has a reasonable safety profile and support clinical development in CDH6-positivie human cancers." (PMID 40871070, 2025). "CUSP06 underwent rapid internalization in CDH6-expressing cancer cells with 50% of CUSP06 being internalized within 4 h upon treatment." (PMID 40871070, 2025). "The preclinical data support the further development of CUSP06 in multiple CDH6-expressing human cancers." (PMID 40871070, 2025). "CUSP06 showed potent antiproliferative activity in the two CDH6-expressing cancer cell lines, with an average GI50 of 0.45 nM (N = 4) and 5.1 nM (N = 4) to OVCAR-3 and PA-1 cells, respectively." (PMID 40871070, 2025). "CUSP06 exhibited strong antiproliferative activity against several CDH6-positive cancer cell lines and demonstrated strong bystander cell killing effect in the cell mixing experiments in vitro." (PMID 40871070, 2025). "The data indicated that the induction of DNA damage and apoptosis by exatecan released from CUSP06 is one of the cytotoxic mechanisms of CUSP06 against CDH6-expressing cancer cells." (PMID 40871070, 2025). "Previous studies have shown that CDH6 expression is increased by TGFβ during epithelial-to-mesenchymal transition in cancer, promoting invasiveness in tumor cells." (PMID 40877928, 2025). "We were particularly interested in CDH6 because of its role in cancer and its potential contribution to aggressive behavior displayed by RA FLS." (PMID 40877928, 2025). "Upon internalization, the exatecan is cleaved from CUSP06 by lysosomal enzymes and leads to the induction of DNA damage and apoptosis of CDH6-positive cancer cells." (PMID 40871070, 2025). "Another study showed that Cadherin-6, a type 2 cadherin that causes EMT during embryonic development, is abnormally increased in cancer and linked with cancer progression." (PMID 40248706, 2025). "The results indicate that the elevated expression of CDH6 is enriched in cancer, MAPK signaling pathway, and other pathways." (PMID 38656888, 2024). "In the results of the current series of RNAseq analyses, Adam8, CA12, and CDH6 were identified as candidates for myCAF-induced cancer-stemness-related genes with secreted proteins." (PMID 37370863, 2023). "Secreted GARS1 interacts with cadherin 6 (CDH6) on neighboring cancer cells, leading to phosphatase 2 A (PP2A) release, which deactivates the ERK signaling pathway." (PMID 35501376, 2022). "CDH6 preferentially bound to αIIbβ3 integrin, a platelet receptor scarcely expressed in cancer cells, and this interaction was mediated through the cadherin Arginine–glycine–aspartic acid (RGD) motif." (PMID 33715292, 2021). "Overall, our study reveals an important mechanism of cancer progression mediated by CDH6 that affects the integrin signaling pathway activation in cancer cell adhesion and invasion." (PMID 33715292, 2021).
cancer (continued). "In contrast, certain cadherins, such as R‐cadherin (CDH4) and K‐cadherin (CDH6), can activate oncogenic pathways critical to cancer progression by regulating the activity of downstream effectors." (PMID 32979859, 2020). "This RGD motif in CDH17 and VE-cadherin enables the activation of α2β1 integrin in different cancers and the activation of αIIbβ3 integrin in CDH6-expressing tumors (manuscript in preparation)." (PMID 31324051, 2019). "On the other hand, we have recently reported that WPS induces an overexpression of cadherin-6 (CDH6) type 2 gene during embryogenesis, which is also involved in the normal development and cancer progression via the initiation of EMT." (PMID 30473629, 2018). "Another study demonstrated that cadherin-6, a type 2 cadherin that induces EMT in embryonic development, is abnormally enhanced in cancer and associated with cancer progression." (PMID 30400561, 2018). "CUSP06 selectively interacts with CDH6 and undergoes rapid internalization into cancer cells." (PMID 40871070, 2025). "Conversely, surface expression of RGD cadherins on circulating cancer cells, particularly CDH6, may facilitate platelet recruitment via αIIbβ3 integrin." (PMID 41039222, 2025). "CDH6 has been shown to be an attractive target for treating certain cancers." (PMID 40877928, 2025). "CDH6 has also been shown to have a role in cancer by affecting cell migration." (PMID 40877928, 2025). "In conclusion, our findings reveal that CDH6 is differentially expressed in RA FLS over OA FLS and plays a significant role in RA FLS pathogenic behavior, sharing regulatory and functional similarities to its role in cancer." (PMID 40877928, 2025). "Pathway enrichment analyses indicated the involvement of CDH6 in multiple biological processes, including cell–cell adhesion, axon guidance, extracellular matrix constituents, transmembrane transporter activity, and several cancer types." (PMID 35938030, 2022). "However, our study found that YAP1 inhibition by verteporfin administration reduced cancer cell viability and stemness and reduced levels of CDH6 and OCT4." (PMID 35356283, 2022). "Different from other mesenchymal biomarkers that are broadly found in cancer, CDH6 may preferentially participate in the late stage of EMT, with direct association with cell invasiveness." (PMID 34281542, 2021). "The duplication of CDH6, αIIbβ3, and α2β1 expression in cancer cells and platelets might facilitate a bidirectional interaction of cancer cells with platelets to facilitate the progression of the metastatic cascade." (PMID 33715292, 2021). "This situation could mimic the two‐step model proposed for platelet binding to collagen; the first step of Glycoprotein VI‐mediated activation of αIIbβ3 in platelets might be mimicked by CDH6 in cancer cells, which will result in the full activation of α2β1." (PMID 33715292, 2021). "Recent studies have shown that CDH6 can be aberrantly overexpressed in cancer." (PMID 34530820, 2021). "On the other hand, CDH6 was also reported to be upregulated in other cancer types." (PMID 32244557, 2020). "However, beyond its role in morphogenesis, platelets and cancer progression (see Section 3.3), little is known about the biological functions of CDH6." (PMID 31324051, 2019). "However, additional genes linked to cancer processes were found deregulated in this study including AHRR, C7, CLPTM1L, and MRPS30 involved in apoptosis, CDH6 in cell adhesion and CEP72 in the cell cycle." (PMID 22412903, 2012). "Therefore, CUSP06 has the potential to be more efficacious than R-DXd in CDH6-low cancers." (PMID 40871070, 2025). "This includes targets such as mesothelin and cadherin 6; the identification of these targets reflects an enhanced understanding of tumor biology and supports the need for personalized treatment strategies that address the unique characteristics of each patient's cancer." (PMID 41347223, 2025).